RBBP5 (RB binding protein 5, histone lysine methyltransferase complex subunit)
Description:
In embryonic stem (ES) cells, plays a crucial role in the differentiation potential, particularly along the neural lineage, regulating gene induction and H3 'Lys-4' methylation at key developmental loci, including that mediated by retinoic acid (By similarity). Does not affect ES cell self-renewal (By similarity). Component or associated component of some histone methyltransferase complexes which regulates transcription through recruitment of those complexes to gene promoters. As part of the MLL1/MLL complex, involved in mono-, di- and trimethylation at 'Lys-4' of histone H3. Histone H3 'Lys-4' methylation represents a specific tag for epigenetic transcriptional activation. In association with ASH2L and WDR5, stimulates the histone methyltransferase activities of KMT2A, KMT2B, KMT2C, KMT2D, SETD1A and SETD1B.
Synonyms: RBQ3; SWD1
Tractability: Small molecule: a structure with a bound ligand is known; a high-quality ligand is known. PROTAC: UniProt records ubiquitination sites on it; ubiquitination databases record sites on it; its protein half-life has been measured; a small molecule that binds it is known.
Gene: Protein-coding gene on chromosome 1 (205,086,142 to 205,122,015, reverse strand). Ensembl gene ENSG00000117222.
Subcellular location: Nucleus
Subcellular location (Human Protein Atlas): Nucleoli; Nucleoplasm
Pathways (Reactome):
Gene expression (Transcription): Epigenetic regulation of gene expression by MLL3 and MLL4 complexes; Formation of WDR5-containing histone-modifying complexes; MLL4 and MLL3 complexes regulate expression of PPARG target genes in adipogenesis and hepatic steatosis; RUNX1 regulates genes involved in megakaryocyte differentiation and platelet function
Developmental Biology: Activation of anterior HOX genes in hindbrain development during early embryogenesis; Differentiation of naive CD4+ T cells to T helper 2 cells (Th2 cells)
Signal Transduction: Deactivation of the beta-catenin transactivating complex; Formation of the beta-catenin:TCF transactivating complex
Chromatin organization: PKMTs methylate histone lysines
Disease: Loss of Function of KMT2D in MLL4 Complex Formation in Kabuki Syndrome
Immune System: Regulation of PD-L1(CD274) transcription
Metabolism of proteins: Neddylation
Gene Ontology:
Molecular function: histone binding; protein binding; transcription cis-regulatory region binding
Biological process: DNA damage response; response to estrogen; transcription initiation-coupled chromatin remodeling
Cellular component: histone methyltransferase complex; MLL1 complex; MLL1/2 complex; MLL3/4 complex; nucleolus; nucleoplasm; nucleus; Set1C/COMPASS complex
Genetic constraint (gnomAD): Loss-of-function variants: 4 observed, 63.78 expected, observed/expected ratio (o/e) 0.0627, 90% interval 0.03 to 0.14. The upper end of that interval is the gene's LOEUF score, 0.14, which puts it in group 1 of 6, group 1 being the genes least tolerant of losing a copy. Missense variants: 312 observed, 632.01 expected, observed/expected ratio (o/e) 0.49, 90% interval 0.45 to 0.54. Synonymous variants: 200 observed, 231 expected, observed/expected ratio (o/e) 0.87, 90% interval 0.77 to 0.97.
Homologues: Orthologues: dog RBBP5 (99% identical), rat Rbbp5 (99% identical), mouse Rbbp5 (99% identical), rabbit RBBP5 (99% identical), chimpanzee RBBP5 (98% identical), macaque RBBP5 (95% identical), tropical clawed frog rbbp5 (92% identical), pig RBBP5 (86% identical), zebrafish rbbp5 (85% identical), Drosophila melanogaster Rbbp5 (61% identical), Caenorhabditis elegans rbbp-5 (35% identical), guinea pig Rbbp5 (28% identical). Paralogues in human: VPS8 (22% identical), WDR72 (17% identical).